CAT (catalase)
Diseases named in the same sentence as CAT in open-access papers (continued):
Sharing a sentence is not in itself a finding about the gene and the disease.
Parkinson disease (continued). "Macrophage carried nanoformulated catalase (nanozyme) attenuates neuroinflammation and protects the nigrostriatal neurons in murine models of Parkinson's disease." (PMID 26082068, 2012). "Based on these studies, it may be concluded that α-synuclein is responsible for both the diminished activity of catalase and the increased formation of hydrogen peroxide, as substantiated by the increased oxidative stress markers in Parkinson’s disease." (PMID 38483584, 2024). "Moreover, animal studies have shown that overexpression of catalase can improve cognitive function and reduce oxidative stress in models of Alzheimer’s and Parkinson’s disease." (PMID 39004753, 2024). "Furthermore, intranasal delivery of catalase-loaded EVs has shown significant neuroprotective effects in the Parkinson’s disease model by reducing stress-induced neuronal death." (PMID 35462907, 2022). "Additionally, γ-Oryzanol prevented neuromotor defects and reduced dopamine by suppressing lipid peroxidation and oxidative stress by upregulating SOD, CAT, and glutathione-S-transferase in the Drosophila melanogaster model of Parkinson’s disease." (PMID 36615764, 2022). "They reported that therapeutic catalase mRNA delivered by designer exosomes, not only attenuated localized neuroinflammation induced by 6-OHDA in vitro and in vivo models of Parkinson’s disease but also rescued neuroinflammation caused by systemic injection of lipopolysaccharide (LPS) in vivo." (PMID 33691652, 2021). "For exosomal small molecular substances, most studies have focused on the loading of chemotherapeutic drugs in exosome, such as incubation of paclitaxel with mesenchymal stem cell (MSC)-derived exosomes to inhibit tumor growth, catalase loading into exosomes to treat Parkinson’s disease (PD)." (PMID 33869195, 2021). "In both in vitro and in vivo Parkinson's disease (PD) models, the transplanted EXOtic device could alleviate neurotoxicity and neuroinflammation by delivering catalase mRNA." (PMID 33437589, 2020). "In more detail, catalase-loaded exosomes in a Parkinson’s disease mouse model showed an increase in the quantity of exosomes with catalase-preserved activity detected in the brain and generated more neuroprotective effects than when administrated intravenously." (PMID 33374908, 2020). "Based on such experiments, it may be concluded that the low catalase activity and high hydrogen peroxide production in Parkinson's disease might be due to (the indirect) inhibition of catalase expression by the α-synuclein molecule." (PMID 31827713, 2019). "Indeed, we have shown the potential of the system for therapeutic applications by demonstrating that catalase mRNA delivery can attenuate neurotoxicity and neuroinflammation in both an in vitro and an in vivo model of Parkinson’s disease." (PMID 29610454, 2018). "Moreover, we showed a potential application of the exosome producer cells equipped with the EXOtic devices in the treatment of Parkinson’s disease by the delivery of catalase mRNA into the brain." (PMID 29610454, 2018). "Therapeutic catalase mRNA delivery by designer exosomes attenuated neurotoxicity and neuroinflammation in in vitro and in vivo models of Parkinson’s disease, indicating the potential usefulness of the EXOtic devices for RNA delivery-based therapeutic applications." (PMID 29610454, 2018). "For example, catalase is a promising treatment for Parkinson's Disease but the inability to transport it across the blood-brain barrier in drug loaded nanoparticles encountered two problems, nanotoxicity of the formulation and activation and rapid clearance of the particles by phagocytosis." (PMID 28289371, 2017). "However, catalase activity is decreased in the substantia nigra of Parkinson’s patients and in the hippocampus of aged humans." (PMID 23536801, 2013).
Parkinson disease (continued). "The prepared FMT-SLNs-PS80 evaluated for their anti-Parkinson’s efficacy in rotenone models in mice showed a significant dose dependent reduction of rotenone induced changes in locomotor activity, muscle strength, and memory, and also levels of CAT, SOD and GSH." (PMID 37968340, 2023). "Mean (SD) superoxide-dismutase (SOD), glutathione-peroxidase (GPx), and catalase activities (expressed as units/mg protein); and concentrations of coenzyme Q10 (expressed in nmol/g protein) in skin fibroblast cultures of patients with Parkinson's disease (PD) and controls (CS = citrate synthase)." (PMID 20958999, 2010). "In LPS-induced Parkinson's disease, limonene significantly reduced oxidative nitrative stress, malondialdehyde (MDA) and nitrite levels, and increased catalase, glutathione (GSH), and superoxide dismutation enzyme (SOD) levels." (PMID 40443223, 2025). "Catalase is known to attenuate neuroinflammation and to reduce Parkinson's disease symptoms, however, the blood brain barrier (BBB) presents a challenge to the effective delivery of catalase." (PMID 38505610, 2024). "As with many other actives, delivery of catalase across the BBB is a major hurdle, however loading of catalase into the exosome carrier system seems to be a promising approach for Parkinson’s disease therapy." (PMID 34204903, 2021). "In a rat model of rotenone-induced Parkinson’s disease, NED maintained cellular SOD, CAT, and GSH and decreased the level of MDA significantly." (PMID 32650602, 2020). "Various studies have reported the decrease in GSH level, and activities of catalase and SOD in the brains of Parkinson’s patients." (PMID 31185705, 2019). "Recently, engineered exosome producer cells implanted in a mouse model of Parkinson disease successfully prevented 6-OHDA-induced cell death by efficient production and delivery of exosomes containing catalase mRNA into the brain, opening the door for new ways to achieve therapeutic effects." (PMID 38020906, 2023). "Fucoidan also attenuated dopaminergic neuron death through potent antioxidative effects such as the inhibition of lipid peroxidation and activation of antioxidant enzyme (SOD, GSH-Px, and catalase) in a 1-methyl-4-phenyl-1, 2, 3, 6-tetrahydropyridine (MPTP)-induced Parkinson’s disease model." (PMID 34436273, 2021).
Insulin resistance (84 papers, 2011 to 2026). Increased resistance towards insulin, that is, diminished effectiveness of insulin in reducing blood glucose levels. "Conversely, chronic blockade of AT1 prevented the insulin resistance-associated decrease in CAT activity indicating the impact of activated AT1 signaling on catalase activity in the heart during insulin resistance." (PMID 29049981, 2018). "(iii) A depletion of RBCs’ reduced glutathione in obese children with insulin resistance is associated with a limited catalase activity." (PMID 29370267, 2018). "As for catalase, it is known that its deficiency is associated with increased intracellular stress which leads to insulin resistance and T2D." (PMID 29410390, 2018). "To determine if increased mitochondrial H2O2 was necessary for loss of mitochondrial CoQ to cause insulin resistance, we over-expressed mitochondria-targeted catalase in the setting of CoQ deficiency." (PMID 29402381, 2018). "Dexamethasone causes insulin resistance and hyperlipidemia leading to cellular lipotoxicity and glucotoxicity responsible for the overproduction of free radicals and therefore a weakening of antioxidant enzymes (CAT, SOD, GSH) in tissues." (PMID 40370420, 2025). "Moreover, the consumption of chokeberry and dried jujube changed the hepatic protein expression of insulin receptor, insulin receptor substrate 1, phosphoinositide 3-kinase, Akt, and catalase, which are associated with insulin resistance." (PMID 31171927, 2019). "Although these facts make it clear that oxidative stress is associated with inflammation, insulin resistance and altered lipid metabolism, the exact contribution of catalase activity to the protection against the progression of these metabolic alterations is not clear." (PMID 27023799, 2016). "Further, catalase deficiency accelerated insulin resistance due to HFD." (PMID 27597806, 2016). "Given the particularly strong association of visceral fat catalase activity with insulin resistance (r = 0.52, P = 0.002) we used multivariate linear regression to investigate whether catalase was an independent predictor of HOMA-IR, after adjustment for its major determinant (BMI), and age." (PMID 28545081, 2017). "Thiazolidinediones (TZD) counteract insulin resistance through its binding to PPARγ, which activates the transcription of antioxidant-associated genes, including superoxide Dismutase1 (SOD) and catalase (CAT)." (PMID 40290438, 2025). "The insulin resistance group exhibited a significant decrease in the activities of CAT, SOD, and GSH-Px (p < 0.05), while the MDA content was notably elevated (p < 0.05) when compared to the blank group." (PMID 40005141, 2025). "The results show that the menthone at a dose of 63.22 μM/mL effectively reduced insulin resistance by enhancing glutathione peroxidase (GPx) and catalase enzyme activity and reactive oxygen species (ROS) reduction in mature 3T3L-1 adipocyte cells." (PMID 40658325, 2025). "Curcumin also enhances antioxidant defenses by activating the Nrf2 pathway, leading to increased expression of enzymes like SOD, catalase, and glutathione peroxidase that are essential in countering oxidative stress and insulin resistance." (PMID 40868165, 2025). "FA can ameliorate hepatic glucose prod disorder caused by insulin resistance through increasing GK, GPx, SOD, and CAT and decreasing the activities of G6Pase and PEPCK." (PMID 36144745, 2022). "Catalase-knockout mice showed exacerbated insulin resistance, amplified oxidative stress, and accelerated macrophage infiltration into white adipose tissues." (PMID 34118873, 2021). "Loganin improved PDN rats’ associated pain behaviors (allodynia and hyperalgesia), insulin resistance index (HOMA-IR), and serum levels of superoxide dismutase (SOD), catalase and glutathione." (PMID 34685668, 2021).
Insulin resistance (continued). "Treatment with Codonopsis lanceolata polysaccharide improved high fat/high sucrose diet-induced insulin resistance via activating antioxidant nuclear factor erythroid 2-related factor 2 signaling and enzymes, such as superoxide dismutase and catalase." (PMID 35002979, 2021). "According to the previous study, activation of CAT is main to the induction of cellular antioxidant system, which can improve insulin resistance in in-vivo study." (PMID 31171927, 2019). "TA-1887-treated mice also showed decreased oxidative stress, which impacts insulin resistance and senescence, as indicated by marker analysis of urine and tissues, potentially due to increased expression of the antioxidative enzymes MnSOD and catalase." (PMID 28900540, 2017). "We found that catalase deficiency increases the M1/M2 ratio in mice on both normal diet (ND) and high-fat diet (HFD) and thereby enhances inflammation and insulin resistance in adipose tissue." (PMID 27597806, 2016). "Catalase knockout (CKO) exacerbated insulin resistance, amplified oxidative stress, and accelerated macrophage infiltration into epididymal white adipose tissue in mice on normal or high-fat diet." (PMID 27597806, 2016). "Taken together, the data indicate that endogenous catalase regulates the polarization of adipose tissue macrophages and thereby inhibits inflammation and insulin resistance." (PMID 27597806, 2016). "Increased levels of plasma glucose, insulin, malondialdehyde, tumor necrosis factor-alpha, and insulin resistance and decreased levels of glutathione, glutathione peroxidase, and catalase were found in rats on a high fructose diet." (PMID 25650289, 2015). "In the present study, the activities of SOD, GPx, and CAT were significantly decreased in the brains of fructose-drinking insulin resistance rats." (PMID 23527159, 2013). "The present study evaluated the effect of P. karwinskii leaves extract on the antioxidant enzymes superoxide dismutase (SOD) and catalase (CAT) in a model of obese rats with insulin resistance for its nutraceutical potential to reduce insulin resistance and oxidative stress." (PMID 39123622, 2024). "In addition, livers of CKO mice showed attenuated insulin-receptor signaling, demonstrating the critical role of catalase as a connecting element between redox homeostasis, liver lipid handling and insulin resistance in vivo." (PMID 35740032, 2022). "Additionally, endogenous catalase regulates the polarization of adipose macrophages, thus inhibiting inflammation and insulin resistance in humans." (PMID 34118873, 2021). "Thereby, increased active oxygen groups result in hepatic oxidative injury and jams of antioxidant enzymes such as SOD (superoxide dismutase), CAT (catalase) and GP (glutathione peroxidase), which further aggravate the progression of insulin resistance and pancreatic β-cell dysfunction." (PMID 34299610, 2021). "Furthermore, catalase specifically targeted to the mitochondria was shown to have protection against some diseases such as cardiac diseases, cancer, and insulin resistance in mice." (PMID 31100095, 2019). "Indeed, the heterozygous deletion of Sod2 and consequent increased mitochondrial O2•– promote insulin resistance in chow-fed mice, whereas SOD2 overexpression, or the expression of mitochondria-targeted catalase attenuate systemic insulin resistance in HFD-fed mice." (PMID 38060313, 2023). "Moreover, we observed that together with SOD, catalase activity was highly upregulated, which might serve as an antioxidant protection against insulin resistance development." (PMID 34732209, 2021). "Moreover, CAT prevented TNF-α-induced insulin resistance in 3T3-L1 adipocytes." (PMID 27023799, 2016). "While the effect of catalase deficiency on the function of adipocytes and hepatocytes remains to be studied, our preliminary data suggest that catalase deficiency also accelerates high-fat diet-induced insulin resistance in WAT and liver (data not shown)." (PMID 27597806, 2016).
Insulin resistance (continued). "↓ Blood glucose, ↓ Insulin resistance, ↓ glycated hemoglobin, preserved pancreatic β-cells integrity, ↓ liver MDA levels, ↑ liver SOD, CAT, and GPx levels." (PMID 40722870, 2025). "↓ Blood glucose, ↓ insulin levels, ↓ insulin resistance, ↓ HOMA-IR, ↑ GLP-1, preserved pancreatic β-cells integrity and function, ↓ liver MDA levels, ↑ liver SOD, CAT, and GSH levels, improved lipidic metabolism, anti-inflammatory activity." (PMID 40722870, 2025). "The males were then likely to develop insulin resistance (hyperinsulinemia), oxidative stress (increased CAT catalase), and hypothyroidism (decreased T4)." (PMID 39453131, 2024). "It has been shown that B1R activation can extend oxidative stress, increasing the production of ROS and antioxidant enzymes such as CAT and SOD in thoracic aorta isolated from rats fed with glucose for 12 weeks, an experimental model of insulin resistance." (PMID 37626696, 2023). "This, in turn, resulted in insulin resistance by the myocardium, a significant downregulation of the endogenous antioxidant enzymes SOD2 and catalase, and diminished LVEF." (PMID 31752330, 2019). "In adulthood, these rats presented overweight, highvisceral adiposity, insulin resistance in the liver, diminished SOD, CAT, and GPxactivity in the liver, and elevated TBARS levels in the liver and plasma, indicatinghigher oxidative stress." (PMID 29791596, 2018). "Notably, these interventions led to decreases in fasting blood glucose (FBG) and homeostatic model assessment of insulin resistance (HOMA-IR), regulating insulin levels while increasing levels of catalase (CAT) and glutathione (GSH)." (PMID 40343290, 2025). "The RB supplementation significantly reduced body weight, body fat, adiposity index, TG, insulin, Homeostatic Model Assessment for Insulin Resistance (HOMA-IR), pro-inflammatory markers (IL-6, and TNF-α), and oxidative stress (MDA, Superoxide dismutase (SOD), and CAT (Catalase))." (PMID 36981226, 2023). "Probiotics reduce insulin resistance and oxidative stress by increasing SOD (superoxide dismutase), GSH (glutathione), and catalase (CAT) activity, and reduce the expression of inflammatory cytokine tissue necrosis factor (TNF)-α, interleukin (IL)-1β, and IL-6." (PMID 37374359, 2023). "Considering the role played by SOD and catalase in the protection of cells against oxidative damage, the increased activity of these enzymes following SFN treatment suggests a decreased hepatic oxidative stress and insulin resistance in SFN-treated rats." (PMID 35779187, 2022). "Interestingly, we demonstrated that naringin can reduced insulin resistance and increase the mRNA expressions of SOD1, CAT, mTOR, and PGC-1α, while showing significantly decreased expressions of Atrogin-1 and MuRF-1 mRNA." (PMID 36235772, 2022). "Naringin not only had improved insulin resistance and increased the gene expression of the antioxidant enzymes (SOD1 and CAT), mTOR, and PGC-1α, but the expressions of IRS-1 and GLUT4 proteins were also increased, which led to increases in the glucose uptake and the glycogen levels." (PMID 36235772, 2022). "In hepatocytes in vitro, upregulation of mitochondrial catalase expression was essential to maintain redox buffer capacity and conversely, catalase deletion in vivo in HFD-fed mice promoted the onset of NAFLD and insulin resistance through mitochondrial dysfunction." (PMID 35740032, 2022). "Catalase (CAT), glutathione peroxidase (GPx), superoxide dismutase (SOD), malondialdehyde (MDA), fasting blood sugar (FBS), insulin, and homeostatic model assessment for insulin resistance (HOMA-IR) were measured in their blood samples." (PMID 31163689, 2019). "Another study demonstrated that catalase deficiency did not cause noticeable changes in mice phenotype up to 10 weeks of age, but accelerated HFD-induced systemic and liver insulin resistance, liver inflammation, along with increased oxidative stress as early as after two weeks of HFD feeding." (PMID 30974751, 2019).
Insulin resistance (continued). "Furthermore, we also found a negative correlation [-0.446 (p = 0.001)] between insulin resistance and catalase activity in the obese groups." (PMID 29370267, 2018). "In the present study, the markedly increased activities of SOD, CAT and GPx as well as significant higher levels of GSH and T-AOC suggested that pioglitazone administration might reduce the ROS production in fructose-drinking insulin resistance rats." (PMID 23527159, 2013). "In addition, in vitro and in vivo experiments showed that DPHC could regulate the antioxidant enzyme levels including superoxide dismutase (SOD), catalase (CAT), and glutathione peroxidase (GSH-Px), thereby reducing the occurrence of oxidative stress and improving insulin resistance." (PMID 35111058, 2021).